DISC1 (DISC1 scaffold protein)
Diseases named in the same sentence as DISC1 in open-access papers (continued):
Sharing a sentence is not in itself a finding about the gene and the disease.
schizophrenia (continued). "Whereas mouse models with mutations in Disc1 have behavioral and pathological alterations characteristic of schizophrenia, efforts to characterize the expression profiles of these key genes have revealed a similar development and functionality to their mammalian homologues." (PMID 23449968, 2012). "More specifically, DISC1 mutations have been associated with deficits in sustained attention and memory in schizophrenia patients, an observation that may be pertinent to the deficits in attention and working memory found in rolandic epilepsy." (PMID 22815793, 2012). "Summary of the associated genes with biological relevance for schizophrenia or the DISC1 pathway." (PMID 22363459, 2012). "In particular, susceptibility genes underlying the pathogenesis of schizophrenia, such as Disrupted-in-schizophrenia 1 (DISC1) and Neuregulin 1 (NRG1), are increasingly being examined within zebrafish to provide novel insights into their role in brain development." (PMID 23449968, 2012). "In addition Pericentrin 2 encoded by Pcnt2 found in the Ms4Yah deleted interval has been associated with schizophrenia and bipolar disorder by several studies and is known to interact with Disc-1." (PMID 21047530, 2011). "In addition, PACAP increases expression of disrupted in schizophrenia 1 (DISC1), which is recognized as a leading candidate risk gene for schizophrenia, and markedly but transiently decreases the association between DISC1 and the DISC1-interacting protein DBZ." (PMID 21524255, 2011). "Indeed Disc-1 is mutated in 129 strains compared to C3H and found identified as genetic risk factor in schizophrenia and affective disorders, inducing deficit in working memory." (PMID 21047530, 2011). "With its interaction with DISC1, it is said to significantly influence the risk for schizophrenia." (PMID 19128481, 2009). "Fifteen studies reported positive association of DISC1 with schizophrenia." (PMID 19128481, 2009). "In addition, recent studies have reported common genes that are involved in both ASD and schizophrenia, for example, association of gene DISC1 (disrupted in schizophrenia 1) and copy number variations in gene NRXN1 (neurexin 1)." (PMID 18632090, 2008). "This study aims to examine the associations between DISC1 interactome genes and specific hallucinations (auditory, visual, somatic, olfactory) and delusions (guilt, reference, grandiose, persecutory, thought control) in individuals with schizophrenia and bipolar disorder in the Mexican population." (PMID 40943654, 2025). "Moreover, genome-wide association studies have reported various schizophrenia risk loci that have been used to create animal models, such as Disrupted-in-Schizophrenia 1 (DISC1), dysbindin-1, neurotrophic factor neuregulin 1 (NRG1) and its receptor, epidermal growth factor receptor 4 (ErbB4)." (PMID 39336117, 2024). "Furthermore, the concept of a signalosome involving disease-associated factors, such as DISC1 and glutamate, may contribute to the multifactorial and polygenic features of schizophrenia." (PMID 36831241, 2023). "In clinical trials, DISC1 missense variants have been found in patients affected by schizophrenia with a form of ultra-resistance to treatment, suggesting that DISC1 variants may have a functional influence on the mechanisms of action of antipsychotics and treatment response." (PMID 36831241, 2023). "In addition to these examples, proteins related to schizophrenia susceptibility could be mentioned, such as DISC1 (Disrupted In Schizophrenia) or dysbindin, both of which have been shown to interact with MTs, MAPs, and actin." (PMID 34025352, 2021). "Consequently, in the present study, we assessed the pattern of development of PNNs related to PVs in the PFC of a genetic mouse model of schizophrenia (129SvEv), harboring mutations in the DISC1 (disrupted-in-schizophrenia) gene compared with controls at different age points." (PMID 34681799, 2021).
schizophrenia (continued). "In addition, these findings strongly suggest that DISC1 alterations may increase the risk of schizophrenia by dysregulating DA release." (PMID 30061532, 2018). "Similarly, the DISC1 haplotype was associated with schizophrenia in a Finnish cohort." (PMID 29467617, 2018). "Thus, the reported loss of MIAT transcript in schizophrenia may regulate the changes in DISC1 and ERBB4 splice variation seen in subjects with schizophrenia." (PMID 29657307, 2018). "Moreover, in vitro rodent studies demonstrated that the schizophrenia-associated gene DISC1 impacts oligodendrocyte differentiation and human genetics have identified oligodendrocyte gene sets associated with schizophrenia, most of them related to fatty acid and cholesterol metabolism." (PMID 29312938, 2017). "Another key implication is that understanding how DISC1 alterations lead to dopamine dysregulation could identify new treatment approaches to address the dopamine dysfunction seen in schizophrenia and people at risk of schizophrenia in a broader sense." (PMID 28140405, 2017). "In contrast, enhanced responsiveness to psychostimulant required prenatal and postnatal continuous expression, which suggests that both neurodevelopmental abnormality and neuronal functional impairment caused by truncated DISC1 might be essential for pathogenesis of schizophrenia." (PMID 25805966, 2015). "Furthermore, many of the genes targeted in these models have multiple associations; for example, DISC1 is associated with bipolar disorder, major depression, social anhedonia, chronic fatigue syndrome, anxiety, neuroticism, emotional stability, schizophrenia, schizoaffective disorder, and ASD." (PMID 25762938, 2015). "Disrupted in schizophrenia-1 (DISC1) gene is associated with several neuropsychiatric disorders as it is disrupted by a balanced translocation involving chromosomes 1 and 11 in a large Scottish pedigree with high prevalence of schizophrenia, bipolar disorder and major depression." (PMID 25126062, 2014). "Furthermore, such interactions, specifically at the level of NMDA receptors, may be relevant for the disorder as several genetic risk factors for schizophrenia, like Dysbindin, reelin and DISC-1, have been shown to alter NMDA-receptor function in rodents." (PMID 22238649, 2012). "Availability of this ‘DISC1 interactome’ has led to a large number of studies that concluded the association of DISC1 to cAMP signaling, axon elongation and neuronal migration, and accelerated the research pertaining to schizophrenia in general and DISC1 in particular." (PMID 23209562, 2012). "A recent study showed that knockdown of endogenous Disrupted-in-schizophrenia 1 (DISC1), a putative susceptibility gene for psychoses such as schizophrenia and bipolar disorder, by small interfering RNA in cortical neurons suppressed phosphorylation of ERK, but the exact mechanisms remain unknown." (PMID 18335055, 2008). "In schizophrenia, decreased expression of the microtubule-associated protein MAP2 and abnormalities in the DISC1 gene have been reported, potentially leading to dendritic morphological abnormalities and neurodevelopmental disorders." (PMID 41972553, 2026). "This overexpression results in DISC1 protein aggregation and aberrant signaling- molecular features identified in a subset of schizophrenia patients identified by elevated DISC1 aggregates in cerebrospinal fluid." (PMID 41639125, 2026). "In the prefrontal cortex of a schizophrenia mouse model (disruption in schizophrenia, DISC1), both PNNs and parvalbumin-positive neurons were decreased." (PMID 40072050, 2025). "The aim of this study has been to further structurally characterize the DISC1 C-region and to understand its significance to the pathophysiology of CMIs such as schizophrenia, MDD and BD." (PMID 40503182, 2025).
schizophrenia (continued). "HERVs contribute to schizophrenia pathogenesis through neuroinflammatory pathways, neurotoxicity, and the dysregulation of risk genes (e.g., BDNF, DISC1, PRODH) via epigenetic and transcriptional mechanisms." (PMID 41200560, 2025). "The disrupted-in-schizophrenia 1 (DISC1) gene is an important gene in schizophrenia and bipolar disorders, and also plays a role in neuroplasticity." (PMID 41007810, 2025). "DISC1 binds to SR, and it has been reported that disruption of the SR–DISC1 complex results in production of schizophrenia-like behavior via depletion of D-serine." (PMID 41008577, 2025). "As for MAM, a model with schizophrenia was studied to determine epigenetic changes around the Drd7 gene and showed differential DNA methylation in the co-factors DISC1, Syp, and Dtnbp1." (PMID 39997929, 2025). "Recent studies have shown that TNIK binds with NMDAR and DISC1, which play important roles in schizophrenia." (PMID 38292191, 2024). "A balanced chromosomal translocation affecting DISC1 locus was initially identified in a large Scottish family with a variety of mental disorders, including schizophrenia, major depression, bipolar disorder, and autism spectrum disorder." (PMID 39604386, 2024). "Recent evidence has highlighted the relevance of PSD proteins, such as PSD-95, Homer, Shank, and DISC1, in the pathophysiology of major psychiatric disorders, including schizophrenia and autism spectrum disorder (ASD)." (PMID 36831241, 2023). "The overlapping risk of BPAD and schizophrenia with MACF1 has also been established through other variants found in schizophrenia and through the interactions between MACF1 and DISC-1 (Disrupted in Schizophrenia)." (PMID 37353479, 2023). "Results from our previous studies demonstrate that ERVWE1 regulates the levels of BDNF and DISC1 in schizophrenia." (PMID 36680208, 2023). "A post-mortem study on the striatum of patients affected by schizophrenia demonstrated an increased interaction between D2R and DISC1 with the formation and accumulation of intraneural complexes." (PMID 36983018, 2023). "Additional efforts to determine higher-level physical brain phenotype changes in schizophrenia return to previous studies of DISC1." (PMID 35948659, 2023). "The linkage between DISC1 abnormalities and developing schizophrenia has been found in humans; however, the DISC1 gene and its clear connection to schizophrenia remain controversial." (PMID 35682647, 2022). "Further studies revealed that DISC1 acts as a scaffold protein regulating multiple schizophrenia-related neuronal development processes through its protein partners." (PMID 36131044, 2022). "In mouse models, it has been shown that the knockdown of Disc1 in the hippocampus leads to deficits in recognition memory and social and anxiety behavior, which are characteristic symptoms of schizophrenia." (PMID 35682647, 2022). "One of the best-described zebrafish models of a human stress disorder is the DISC1 (Disrupted-in-schizophrenia 1) zebrafish." (PMID 36632608, 2022). "The DISC1 gene was originally identified in a Scottish family in which a chromosomal translocation directly disrupts the DISC1 gene, leading to several mental disorders including schizophrenia and recurrent major depression." (PMID 35715502, 2022). "Overexpression of full-length DISC-1 and the resulting protein aggregation has been found to trigger the development of behavioral and molecular phenotypes that can also be seen in schizophrenia." (PMID 36430976, 2022). "DISC1 can also regulate neurogenesis, neurite outgrowth, and synaptic plasticity, which are all involved in the pathogenesis of schizophrenia." (PMID 36131044, 2022). "In contrast, prolonged knockdown of DISC1 expression leads to a reduction in spine density in the cortical neurons, analogous to the synaptic pathology of schizophrenia." (PMID 36301793, 2022). "Notably, DISC1 might interact with other schizophrenia susceptibility factors." (PMID 36590092, 2022).
schizophrenia (continued). "Advantages: Such a genetic model allows us to carefully study the role of the Disc-1 protein in various neuronal processes related to schizophrenia." (PMID 35682647, 2022). "Another example is DISC1 (disrupted in schizophrenia 1), which is perhaps the best characterized generalized risk factor for major psychiatric disorders." (PMID 36344514, 2022). "It was demonstrated that the decrease in total or functional DISC-1 led to impaired sensorimotor gating, which often occurs in patients with schizophrenia." (PMID 36430976, 2022). "DISC1 is involved in the pathology of psychiatric disorders including schizophrenia, bipolar disorder, and depression." (PMID 35493069, 2022). "The Disrupted-in-Schizophrenia 1 (DISC1) signaling pathway is considered to play a role in different psychiatric disorders such as schizophrenia, depression, and biopolar disorders." (PMID 35715502, 2022). "In a different study, disturbances in the GABAergic system were observed in DISC1 knockout mice, such as a decreased GABAergic neuron density in the cortex, suggesting that the GABAergic neuronal system is an important system for schizophrenia pathogenesis." (PMID 35682647, 2022). "In this regard, we postulate that the DISC1-Δ3 in OPCs mediates a ‘gain-of-function’ to promote the hyperactivity of the Wnt/β-catenin signaling pathway in schizophrenia brains." (PMID 36131044, 2022). "It is known that DISC1 binds directly with Pde4b and Gsk3β, two molecules involved in schizophrenia pathology." (PMID 36590092, 2022). "Taken together, our results reveal hypertrophic morphology of OPCs in both schizophrenia patients and DISC1-Δ3 mice." (PMID 36131044, 2022). "Taken together, our results from the DISC1-Δ3 mouse model indicate that Wnt-hyperactivation in the OPCs can disrupt synapse formation and initiate the pathogenesis of schizophrenia by overproduction of Wnt inhibitor Wif1." (PMID 36131044, 2022). "Attenuated reactivity of the HPA axis was reported in a transgenic mouse strain carrying an inducible mutant human DISC1 gene prenatally challenged with polyI:C, a preclinical model of schizophrenia." (PMID 36632608, 2022). "The phosphodiesterase, PDE4A, which catabolizes cAMP, is also localized next to the spine apparatus, and is anchored there by DISC1 (disrupted in schizophrenia 1)." (PMID 33319854, 2021). "For example, genetic variations in the genes encoding for DISC1, mGluR3, COMT, and RGS4 interact to increase risk of schizophrenia, and these proteins are all found in primate layer III microcircuits in dlPFC." (PMID 33319854, 2021). "Disrupted schizophrenia 1 (DISC1) is a strong candidate gene for major psychiatric disorders such as schizophrenia and autism spectrum disorders." (PMID 34746116, 2021). "The atypical antipsychotic drug clozapine alleviates these aberrant alterations, and additional research on DISC1 has elucidated its potential to regulate neurogenic capacity and schizophrenia-like impairments in hippocampal-related cognitive tests." (PMID 33785869, 2021). "One in particular is Disrupted-in-Schizophrenia-1 (DISC1), whose name alludes to its correlation with the neurodevelopmental disease schizophrenia." (PMID 35053800, 2021). "Similar phenotypes have been repeatedly reported in many of animal models for schizophrenia or bipolar disorder including Disc1 gene modified mice." (PMID 33656268, 2021). "For instance, the role for DISC1 in the development of schizophrenia has been repeatedly reported in previous preclinical animal model studies." (PMID 34746116, 2021). "There are also important genetic links with schizophrenia risk and proteins already known to inhibit cAMP signaling in dlPFC spines, including mGluR3 (GRM3) and DISC1, which normally serves to anchor PDE4s to the spine apparatus." (PMID 33319854, 2021).
schizophrenia (continued). "For instance, how can we translate the structural and biophysical information to other mutants of the DISC1 C-region relevant in schizophrenia pathophysiology, such as the S704C, S713E, and L807 (frameshift) to name a few?" (PMID 34921141, 2021). "For example, proteins encoded by genes linked to schizophrenia, such as dysbindin, disrupted one in schizophrenia (DISC1) and collapsin response mediator proteins (CRMPs) were found to localize with and regulate the actin cytoskeleton in neurons." (PMID 34440848, 2021). "In schizophrenia, DISC1 and PHB2, another mitophagy-related factor, are commonly found upregulated, causing alterations in mitophagy." (PMID 33918863, 2021). "To comprehend the impact of DISC1 on the pathophysiology of schizophrenia and related CMIs, we focus our efforts on the C-region of the protein." (PMID 34921141, 2021). "Therefore, in this study, we employed a DISC1 (Disruption in Schizophrenia) mutation mouse model of schizophrenia to assess these developmental changes and tested whether enzymatic digestion of PNNs in the PFC affected schizophrenia-like behaviors and neural activity." (PMID 34681799, 2021). "Disrupted in schizophrenia 1 (DISC1) protein is a cAMP effector protein; low levels of DISC1 are correlated with schizophrenia." (PMID 34149352, 2021). "Our study provided further support for the involvement of DISC1 in the development of schizophrenia." (PMID 33008326, 2020). "While it has been intensely studied for its potential role in schizophrenia, decreased levels of DISC1 expression have also been reported in PBMCs from patients with BD compared to controls." (PMID 32846922, 2020). "Thus, DISC1-related polymorphisms may contribute to neurodevelopmental alterations, as well as changes in white matter integrity, participating in the etiology of schizophrenia." (PMID 32425837, 2020). "Research on DISC1 and psychiatric disorders has generated many new insights into the origins of schizophrenia, especially the role of DISC1 in cortical neurogenesis, neuroblast migration and early development." (PMID 32493513, 2020). "We found that the DISC1-D2R complex is elevated in post-mortem brain samples from patients with schizophrenia, and in Disc1-L100P mutant mice, an animal model for schizophrenia." (PMID 32493513, 2020). "Another study using cultured neurons and mouse brain showed that TLR3 suppresses disrupted in schizophrenia 1 (Disc1) expression and consequently neuronal development." (PMID 31959813, 2020). "Lipina T.V., Niwa M., Jaaro-Peled H., Fletcher P.J., Seeman P.,Sawa A., Roder J.C. Enhanced dopamine function in DISC1-L100P mutant mice: implications for schizophrenia." (PMID 33959693, 2020). "The outsized contribution of DISC1 in the neuropathogenesis of schizophrenia is largely attributable to its role in early neurodevelopment." (PMID 32102223, 2020). "In this sense, there is evidence showing that SCZ patients exhibit an accumulation of Disc1 (Disrupted-in-schizophrenia 1) aggregates." (PMID 32092878, 2020). "Studies have shown that oligodendrocyte differentiation is impaired in schizophrenia and that DISC1 negatively regulates the differentiation of oligodendrocyte precursors." (PMID 33390896, 2020). "Beyond inflammation, lncRNA that target the schizophrenia candidate gene Disrupted in Schizophrenia (DISC1) have also been reported in BD." (PMID 32846922, 2020). "Expression of a fusion protein of DISC1 and Boymaw [also called DISC1FP1, a potential outcome of a schizophrenia-associated chromosomal translocation] drastically reduces mitochondrial transport and also mitochondrial fusion." (PMID 32637409, 2020). "In this study, we compared DISC1 expression levels in blood of 48 healthy controls, and 32 schizophrenia patients before and after 12 weeks of antipsychotic treatment using real-time quantitative PCR (RT-qPCR) analysis." (PMID 33008326, 2020).